CTLA4 (cytotoxic T-lymphocyte associated protein 4)
Diseases named in the same sentence as CTLA4 in open-access papers (continued):
Sharing a sentence is not in itself a finding about the gene and the disease.
cancer (continued). "In cancer patients, the CTLA-4 and PD-1 molecules on effector T cells are upregulated and, respectively, bind to B7-1/B7-2 and PD-L1 of antigen-presenting cells or tumor cells." (PMID 36077696, 2022). "In the new era of immunotherapies, ICIs, including antibodies against PD-1 (nivolumab) and CTLA4 (ipilimumab), are widely used for cancer treatment." (PMID 36466840, 2022). "The latest research has emphasized novel combined methods that integrate anti-CTLA-4 with other ICBs or traditional treatments to greatly enhance the efficacy of immunotherapy in many cancer types." (PMID 36084948, 2022). "Recently, immune checkpoint inhibitors (ICIs), including antibodies targeting programmed death-1 (PD-1) receptor, its ligand (PD-L1), and cytotoxic T lymphocyte associated protein 4 (CTLA-4), have become the main means of cancer treatment." (PMID 36057262, 2022). "Immune checkpoint antagonists targeting PD-1, PD-L1, and CTLA-4 have reformed cancer therapy and demonstrated the power of treating the immune system benefiting multiple cancer types." (PMID 35317079, 2022). "Current immunotherapies for cancer indeed include CTLA-4 inhibitors, which have been shown to be effective against various cancers, including metastatic melanoma." (PMID 36231078, 2022). "Immunotherapies that use antibodies directed to inhibitory immune checkpoints—such as PD-L1, PD-1 and CTLA-4—have introduced a major breakthrough in cancer therapy, with relatively good impact on disease course, primarily in melanoma." (PMID 35205789, 2022). "Immunotherapies represented by the PD-1/PD-L1 and CTLA-4/B7 pathways have shown significant clinical efficacy in a variety of cancer types." (PMID 35510040, 2022). "A randomized controlled trial in cancer patients, reported decreased numbers of circulating Treg cells in patients who experienced irAEs on anti-CTLA-4 treatment." (PMID 36713389, 2022). "High doses of anti-CTLA-4, as used in preclinical cancer immunotherapy studies (“oncological dosing”), worsened survival, whereas a 4- to 6-fold lower dose of anti-CTLA-4 improved survival outcomes." (PMID 36389687, 2022). "Immune checkpoint inhibitors (ICIs), such as anti-CTLA4, anti-PD-1 and anti-PD-L1 antibodies, show promising efficacy in a wide range of cancer types and represent a breakthrough in cancer therapy." (PMID 36071036, 2022). "There are six drugs targeting PD-1 or PDL-1 and only one targeting CTLA-4 currently approved for use in therapy of different types of cancer." (PMID 35301281, 2022). "Immunotherapies represented by PD-1 and CTLA4 blockades have undoubtedly emerged as a major breakthrough in cancer therapy." (PMID 36120583, 2022). "ICIs targeting PD-1, PD-L1, and CTLA-4 have rapidly become a major cancer treatment option over the past decade." (PMID 35681672, 2022). "ICI can significantly improve survival duration and quality of living in a variety of cancers through the inhibition of CTLA-4 or PD-1 pathways." (PMID 36568254, 2022). "Anti-PD-1/PD-L1 antibodies alone in monotherapy or combined with anti-CTLA-4 antibodies or different chemotherapy agents have demonstrated unprecedented clinical efficacy and durable responses in more than 15 cancer types in the advanced setting." (PMID 36140517, 2022). "Immune checkpoint inhibitors (ICIs) targeting cytotoxic T-lymphocyte-associated antigen 4 (CTLA-4), programmed cell death protein (PD-1), and its ligand PDL-1, are finding increasing application in the treatment of malignant neoplasms." (PMID 35204486, 2022). "In the past few years, most studies regarding the field of cancer immunotherapy have been focusing on a few checkpoint molecules including, PD-1/PD-L1 and CTLA-4." (PMID 35814211, 2022). "In the past decade, anti-cancer immunotherapies targeting PD-1/PD-L1 and CTLA-4, have achieved positive response in HCC patients." (PMID 35493471, 2022).
cancer (continued). "As targeted programmed death-ligand 1 (PD-L1), programmed death 1 (PD-1) and cytotoxic T lymphocyte-associated protein 4 (CTLA4), the existed ICB treatment has significantly improved the overall survival (OS) of patients in several cancers." (PMID 35614936, 2022). "Targeting immune checkpoints by anti-PD1/PD-L1 and anti-CTLA4 antibodies has revolutionised anti-cancer therapy." (PMID 36138076, 2022). "CTLA4 and PD-1 inhibition are two examples of immunotherapy that have achieved significant advances in cancer treatment." (PMID 35903107, 2022). "After the discovery of the roles of checkpoint molecules such as PD-1, its ligand PD-L1, and CTLA-4, efforts have been redirected toward developing antibodies to inhibit their activity and release the patient's own immune system to fight cancer." (PMID 36686160, 2022). "The IPS values (ips_ctla4_neg_pd1_pos, ips_ctla4_pos_pd1_neg, ips_ctla4_pos_pd1_neg, and ips_ctla4_pos_pd1_pos) have been validated in predicting cancer patients’ responses to anti-CTLA-4 treatment." (PMID 36246623, 2022). "Immunotherapies based on CTLA-4/PD-1/PD-L1 inhibitors have achieved astounding clinical efficacy in malignant tumor therapy." (PMID 35155433, 2022). "This article is an in-depth analysis of the proposed mechanisms of anti-CTLA-4 therapy and its newfound uses in cancer treatment." (PMID 35326731, 2022). "Cancer cells can acquire immune regulatory surface proteins like CTLA-4, which suppress the activation of immune cells, such as T cells." (PMID 35600409, 2022). "The expression of immune-inhibitory checkpoints like CTLA-4 and PD-1/PD-L1 has recently been proven to be an effective mediator for controlling and evading phases of cancer-immune editing." (PMID 36363529, 2022). "Circulating TEV carrying CTLA-4 were also detected in cancer patients, and their concentration correlated with a poor outcome." (PMID 36011012, 2022). "Another approach with promising preclinical findings is combining cancer vaccines and simultaneously blocking CTLA-4 and PD-1." (PMID 35651800, 2022). "Evidence from mouse studies suggests efficacy in cancer treatment, especially in combination with either anti-PD-1 or anti-CTLA-4 therapy." (PMID 35784333, 2022). "Immune checkpoint inhibitors (ICIs) are monoclonal antibodies that block CTLA-4, PD-1, or PD-L1 and induce the activation of the immune system against cancer." (PMID 35433707, 2022). "Clinical advances in cancer immunotherapies that target immune checkpoint receptors (CTLA-4 and PD-1) have shown the relevance of immunoevasion as a specificity of malignancy and cancer." (PMID 36428613, 2022). "Tregs contribution to immune tolerance is well known, and anti-CTLA-4 monoclonal antibodies were used to target them in cancer patients with some success." (PMID 36428632, 2022). "CTLA-4 mAb is also of great clinical significance in hematologic malignancies such as AML and MDS and has great potential in combination with CD73 antibody in the treatment of malignant diseases of the blood." (PMID 36159861, 2022). "At present, programmed cell death 1/programmed cell death ligand 1 (PD1/PDL1) and cytotoxic T lymphocyte-associated protein 4 (CTLA4) are the most well-studied signals and have shown impressive therapeutic benefits in different cancers." (PMID 35574031, 2022). "Considering that ICB cancer immunotherapy works by inhibiting key immune checkpoints, we assessed certain representative molecules and discovered that PD-1, PD-L1, and CTLA4 were significantly more increasingly expressed in the high RiskScore group." (PMID 36482907, 2022). "Antibodies against CTLA-4 and PD-1 can block these two molecules that are highly expressed on the surface of cancer cells, promote T cell activation, and then kill cancer cells." (PMID 36138905, 2022). "Immunotherapy represents one of the most important advancements in the cancer therapy field, since inhibitors of immune checkpoints CTLA4, PD-1 and PD-L1 dramatically improved therapeutic results." (PMID 36224560, 2022).
cancer (continued). "The introduction of immune checkpoint inhibitors (ICI), such as anti-PD-1/PD-L1 and anti-CTLA-4, has become a new game changer in the treatment of an ever-growing number of cancer types." (PMID 36140517, 2022). "The appliance of immune checkpoint inhibitors (ICIs), particularly anti-PD1/PD-L1 and anti-CTLA4, has revolutionized the treatment of cancer." (PMID 36189319, 2022). "Preclinical studies showed that blockade of CTLA4 or PD-1 repressed tumor growth, which provide pioneering evidence for treating cancer patients with immune checkpoint inhibitors." (PMID 35372044, 2022). "Targeting the CTLA-4 signaling pathway by antibodies or fusion proteins has attracted significant attention in the field of cancer therapy." (PMID 35585975, 2022). "The CTLA-4 and PD-1/PD-L1 blockade has emerged as a critical weapon in treating cancer (Postow, Callahan & Wolchok, 2015)." (PMID 35127296, 2022). "Monoclonal antibodies to CTLA-4 and PD-1 or PD-L1 therefore remove the inhibition and allow the body to enhance its immune response to the cancer through restoring cytotoxic T cell activation." (PMID 38983573, 2022). "At present, using antibodies against immune checkpoints PD-1, PD-L1 or CTLA-4 is the main type of immunotherapy available to cancer patients." (PMID 35805044, 2022). "Immunotherapies focusing on rejuvenating T cell activities, like PD-1/PD-L1 and CTLA-4 blockade, have unprecedentedly revolutionized the landscape of cancer treatment." (PMID 35967421, 2022). "ICIs targeting cytotoxic T-lymphocyte protein 4 (CTLA-4) and programmed death receptor-1 (PD-1) pathways have induced durable treatment responses in a wide variety of cancers." (PMID 36741738, 2022). "Because anti-CTLA-4 antibody and anti-PD-1 antibody (or anti-PD-L1 antibody) work in different ways, they have synergistic effects when used in combination in many cancers." (PMID 35433482, 2022). "According to the present findings, LAG-3 is a promising cancer therapeutic target secondary to PD-1/PD-L1 and CTLA-4." (PMID 35874717, 2022). "Immunotherapies targeting the CTLA-4 pathway have shown remarkable clinical efficacy against many cancer types, such as prostate, cervical, gastric, pancreatic, ovarian, and urothelial cancers and melanoma." (PMID 35550532, 2022). "As more and more ICIs have been proven to be effective in cancer treatment in recent years, we further evaluated the expression of PD-1, PD-L1, CTLA4, and HAVCR2." (PMID 36160015, 2022). "Positive correlations were also observed between the TR-DDR score and expression of PD1 and CTLA4 in 8 cancer types." (PMID 36081518, 2022). "Immune checkpoint inhibitors (ICIs), such as atezolizumab and avelumab, which target PD−L1, pembrolizumab and nivolumab, which target PD-1, and tremelimumab, which targets CTLA-4, have been applied as cancer immunotherapy during the past few decades." (PMID 35154121, 2022). "Despite efficient and similar anti-cancer activity, immunophenotyping analysis demonstrates different cellular mechanisms between CTLA-4 and PD-1 blocking strategies." (PMID 35339889, 2022). "Immune checkpoint inhibitors have shown durable responses with the inhibition of PD-1 and CTLA-4 in other cancers; however, when applied to the treatment of GBM, improved outcomes have remained elusive." (PMID 35203636, 2022). "Inhibitory co-receptors such as PD-1 and CTLA-4 have become prominent targets for immune checkpoint inhibition in cancer immunotherapy, allowing for T cells to be activated in cancerous environments." (PMID 35327505, 2022). "LINC00857 expression had a significant reverse correlation with PD-1, PD-L1 and CTLA-4 expression in these cancers." (PMID 36160408, 2022). "Immune checkpoint inhibitor (ICI) therapies based on anti-CTLA-4 and anti-PD-1/PD-L1 antibodies have been extensively explored over the recent years to unleash otherwise compromised anti-cancer immune responses." (PMID 35428302, 2022).
cancer (continued). "The success in preclinical models has led to the development of humanized monoclonal antibodies to inhibit the interaction of CTLA-4 with its ligand (B7) in patients with cancer and the establishment of clinical trials." (PMID 36648843, 2022). "This is illustrated by the recent expansion of the use of immunotherapies such as immune checkpoint inhibitors (CTLA-4, PD-1 and PD-L1), which harness the host immune system to generate powerful anti-cancer effects." (PMID 35655772, 2022). "For example, immune checkpoint (PD-1, CTLA-4) blockade has become an increasingly important part of cancer therapy." (PMID 35664334, 2022). "Immune checkpoint blockade targeting CTLA‐4 and PD‐1 has become a new standard of care, referred to as cancer immunotherapy." (PMID 34270845, 2022). "Since 2000, immune checkpoint inhibitors such as ipilimumab and tremelimumab, CTLA-4 inhibitors that are used in a new and effective treatment strategy for immunotherapy in cancer, have been in clinical development." (PMID 35281086, 2022). "Immune checkpoint blockade (ICB) therapies, including inhibition of programmed cell death 1 (PD-1) or ligand 1 (PD-L1) and cytotoxic T-lymphocyte antigen-4 (CTLA-4), have been able to induce a lasting response across multiple cancer lineages." (PMID 36273184, 2022). "Blocking the immune checkpoint therapy (such as PD-1 and CTLA-4) is a promising approach for various cancer." (PMID 36313774, 2022). "The inhibitory function of both CTLA-4 and the PD-1/PD-L-1 axis makes them important therapeutic targets against cancer." (PMID 35566754, 2022). "Cancer immunotherapies, such as administration of the cytokine Interleukin-2 (IL-2), adoptive cell transfer, and the checkpoint modulators CTLA-4 and PD-1, have proved effective in clinical practice." (PMID 35651784, 2022). "As a practical approach, anti-PD-1 and anti-CTLA-4 antibodies are entering in cancer treatment, and the number of individuals treated with such drugs will increase exponentially in the future." (PMID 35145371, 2022). "T-cell immune checkpoint inhibitors are most common and successful agents used in cancer immunotherapy, which would activate the immune system through targeting cancer immune checkpoints such as PD-1/PD-L1, CTLA-4, and block immunosuppression signals." (PMID 35422796, 2022). "When expressed by cancer cells, CTLA-4 has also been shown to suppress the maturation and functions of DCs23,24." (PMID 35304456, 2022). "Some studies have proven that the expression of PD1/PD-L1 and CTLA-4, microsatellite instability (MSI) status, and mutation load are not effective for predicting the immune response in different types of cancer." (PMID 35154121, 2022). "Recent advents in cancer immunology led to the development of novel therapies, including immune checkpoint blockades (ICBs) against PD-1 and CTLA-4, chimeric antigen receptor (CAR) T cells, and recombinant cancer vaccines." (PMID 35205315, 2022). "The achievement of successful treatment results has made PD-1/CTLA4 inhibition available to an increasing number of cancer patients." (PMID 35455289, 2022). "In patients with cancer, lymphocytes can experience chronic exhaustion and express PD-1 and CTLA-4 co-inhibitory receptors." (PMID 36686160, 2022). "The mechanism involved in the targeted CTLA-4 vs. PD-1/PD-L1 in cancer treatment are not well understood." (PMID 36355837, 2022). "Immunotherapy represented by anti-PD-1/PD-L1 or CTLA-4 antibody had broadened the field of cancer treatment and brought huge clinical benefits in recent years." (PMID 36276973, 2022). "Several potential immunotherapy target agents, including anti-CTLA4, anti-PD-1/PD-L1, cancer vaccines, and adoptive cell therapy, have become prominent in immunotherapy-based clinical trials for GC." (PMID 35144613, 2022). "In recent years, the use of immune-checkpoint inhibitors (ICIs), such as targeting PD-1/PD-L1 or CTLA4, has markedly changed the field of cancer treatments." (PMID 35242761, 2022).
cancer (continued). "Immune checkpoint blockade (ICB), therapies that target the PD-1 pathway, CTLA-4 pathway, and other checkpoint pathways, lead to durable responses in many cancer types." (PMID 35309122, 2022). "Cotargeting CTLA-4 and PD-1/PD-L1 immune checkpoints simultaneously with their respective blocking mAbs is the most efficacious strategy currently available for cancer immunotherapy." (PMID 35239514, 2022). "Cancer cells exploit immune checkpoints (CTLA-4, PD-1, PD-L1, and PD-L2) to break the physiologic maintenance of self-tolerance and inhibit the antitumor immune response." (PMID 36380313, 2022). "The evolving immunotherapies which include PD-L1, PD-1, and CTLA4 suppressors have led to extremely effectual antitumor impacts in cancer therapies." (PMID 35855850, 2022). "Cancer immunotherapy utilizing immune-checkpoint inhibitors (ICI), such as, CTLA4 (cytotoxic T-lymphocyte-associated protein 4), PD1 (programmed cell death protein 1), and PDL1 (ligand for PD1), have revolutionized the field of cancer treatment." (PMID 35741331, 2022). "Especially, high expression of LAG3, CTLA4, PDCD1 (PD-1), IDO1, and CD274 (PD-L1) were widely reported to be associated with suppressive immune response and suppressed T cell function in cancer." (PMID 35902970, 2022). "Immune checkpoint inhibitors (ICI) targeting cytotoxic T-lymphocyte-associated protein 4 (CTLA-4), programmed cell death protein 1 and its ligand (PD-1/PD-L1) have become the current standard-of-care for many advanced cancers." (PMID 36419114, 2022). "This review will discuss proposed fundamental mechanisms of anti-CTLA-4 therapy, novel uses of anti-CTLA-4 in cancer treatment and approaches to improve the therapeutic efficacy of anti-CTLA-4." (PMID 35326731, 2022). "The targets for these agents include CTLA-4, PD-1, and PD-L1, which are involved in many malignant tumors." (PMID 35743107, 2022). "Nowadays, immune checkpoint blockades targeting CTLA-4 and PD-1 has emerged as a promising strategy in various malignant tumor." (PMID 35205261, 2022). "ICIs, such as anti-PD-L1, anti-PD-1, and anti-CTLA-4 antibodies, have contributed to immunotherapy in cancers." (PMID 35592314, 2022). "Both PD-1/PD-L1 and CTLA-4 antibodies have shown substantial efficacy in treating malignancies on their own and have been authorized for marketing by the FDA." (PMID 35401745, 2022). "We found that CM patients in the low-cTMGs group had a significantly higher response to ACT, MAGE-A3 antigen-specific cancer immunotherapy, anti-PD-1 monotherapy, or anti-PD-1/anti-CTLA-4 combined therapy compared with those in the high-cTMGs group." (PMID 36072600, 2022). "Immunotherapy is emerging as an important modality in the treatment of cancer, such as ICB targeting CTLA-4 and PD-1 and its ligand (PD-L1), which can be used to treat tumors by reactivating anti-cancer immune responses." (PMID 35685442, 2022). "In recent years, the discovery of the immune checkpoints, such as programmed cell death 1(PD-1) and cytotoxic T lymphocyte antigen 4 (CTLA-4), has also greatly changed treatment methods and ideas for malignant tumors." (PMID 36159861, 2022). "Then, anti-CTLA-4, anti-PD-1 and anti-PD-L1 monoclonal antibodies and other immune checkpoint inhibitors have been markedly successful in treating diverse cancer patients with melanoma, non–small-cell lung cancer, and ovarian cancer." (PMID 36284271, 2022). "Immune checkpoint inhibitors (ICIs), monoclonal antibodies directed against immune checkpoint molecules such as PD-1, PD-L1, and CTLA-4, are the newest addition to cancer therapy." (PMID 35418578, 2022). "Thereby, ICIs prevent engagement of PD-1 and CTLA-4 with their corresponding ligands, enabling the immune system to mount potent antitumor immune response by reinvigorating T cells against cancer cells." (PMID 35173722, 2022).